EXO1 (exonuclease 1)
Diseases named in the same sentence as EXO1 in open-access papers (continued):
Sharing a sentence is not in itself a finding about the gene and the disease.
cervical carcinoma (8 papers, 2013 to 2025). A carcinoma arising from either the exocervical squamous epithelium or the endocervical glandular epithelium. "EXO1 is highly expressed in several cancers, including colorectal, breast, lung, prostate, and cervical cancers." (PMID 38279172, 2024). "We found that EXO1 was highly expressed in cervical cancer and was verified by immunohistochemistry." (PMID 35449547, 2022). "Several non-synonymous SNPs and non-coding SNPs in the gene promoter including rs10802996, a SNP associated with cervical cancer, and in the 3′ UTR sequences to downstream of EXO1 showed significant associations with the risk of UL and the 4-level tumor growth outcome." (PMID 23555580, 2013). "EXO1 rs1047840 GA genotype appeared to contribute to a CR and marked hematological toxicity seen in a patient with laryngeal cancer treated with CDDP and RT, and variant allele “A” of EXO1 rs1047840 was also associated with a better response rate in patients with cervical carcinoma." (PMID 30038702, 2018). "The percentage of EXO1 gene alterations was 16% in BRCA samples, 6% in uterus cancer samples, 0.8% in THCA samples, 7% in OV samples and 2.6% in cervix cancer samples." (PMID 40433389, 2025). "The outcomes of this assessment substantiated our preliminary observations, revealing the upregulation of RRM2 and VEGFA, alongside the downregulation of RFC4, EXO1, PCNA, TOP2A, and TYMS in cervical cancer tissues relative to normal cervical epithelial tissues." (PMID 38926832, 2024).
lymphoma (8 papers, 2013 to 2022). A malignant (clonal) proliferation of B- lymphocytes or T- lymphocytes which involves the lymph nodes, bone marrow and/or extranodal sites. "EXO1 inactivation also reduced overall survival in mice and caused an increased incidence of cancers, especially lymphomas." (PMID 35849338, 2022). "In other organisms, EXO1 is fundamental for DNA repair, and its deficiency is associated with increased susceptibility to lymphomas in knockout mice." (PMID 35059327, 2021). "Wei indicated that mammalian EXO1 is responsible for mutation prevention and mice EXO1 inactivation reduced survival time and increased risk of lymphoma." (PMID 27894089, 2016). "EXO1 mutant mice were reported to have reduced survival and increased susceptibility to lymphoma development." (PMID 24147022, 2013). "Apart from the reported polymorphisms and elevated expression of EXO1 in Ductal carcinoma in situ, also there are contradicting reports relating EXO1 loss of function to increased susceptibility to lymphomas, urging the need for further investigation." (PMID 24147022, 2013). "EXO1 was significantly increased in BLV-infected cattle with lymphoma compared with uninfected and infected cattle." (PMID 33143351, 2020). "EXO1 was expressed at significantly higher levels in infected cattle with lymphoma than in uninfected cattle and BLV-infected cattle." (PMID 33143351, 2020). "Furthermore, Exo1DA/DA and Exo1–/- mice exhibited similarly reduced survival due to the development of lymphomas, sarcomas, and gastrointestinal adenocarcinomas." (PMID 35849338, 2022). "A possible piece of evidence suggesting the involvement of EXO1 in double strand DNA repair is the observation that Exo1null/null mice show an increase in chromosomal breaks and base substitution, and predominately develop lymphomas." (PMID 30585186, 2018). "The clinical data is supported by mouse models, where the loss of Exo1 leads to an increased incidence of lymphomas, but interestingly not to increased MSI." (PMID 30585186, 2018). "EXO1 was significantly increased in BLV-infected cattle with lymphoma compared within uninfected cattle and BLV-infected cattle without lymphoma." (PMID 33143351, 2020).
colon carcinoma (6 papers, 2011 to 2024). "The present paper examines the impact of polymorphisms of PolB, LIG3, and EXO1 of the BER repair system on the modulation of the risk of colon cancer." (PMID 26649135, 2016). "We have found significantly increased transcription levels in EXO1 gene in tumor tissues (P = 0.05) and significant over-expression of MSH3 gene in colon tumors when compared to adjacent mucosal tissues (P = 0.02)." (PMID 24484585, 2014). "They found that amygdalin down‐regulated the cell cycle‐related genes: ATP‐binding cassette, exonuclease 1 (EXO1), sub‐family F and topoisomerase (DNA) I (TOP1) in SNU‐C4human colon cancer cells, thereby affecting tumor cell cycle, inhibiting cell proliferation and exerting its antitumor effect." (PMID 31066207, 2019). "APC and CMTM3, EXO1 and HLTF are reported to be hyper-methylated in selected colon cancer samples." (PMID 22051105, 2011).
melanoma (6 papers, 2015 to 2025). A malignant, usually aggressive tumor composed of atypical, neoplastic melanocytes. "In family F1288, though the mother of the index EXO1 c.1268-1G>T carrier case (PT0158) with BC and melanoma also carried the EXO1 variant, her sibling (PT0180) and maternal female cousin (PT0181) both with BC were not carriers of the EXO1 variant." (PMID 36969007, 2023). "FOXM1, KIF20A, TPX2, CDC20, and EXO1 are hub genes of melanoma prognostic, and their high expression is strongly associated with low prognosis in melanoma patients." (PMID 33912448, 2021). "The protein expression of FOXM1, KIF20A, TPX2, CDC20, and EXO1 was higher in melanoma than in paraneoplastic tissues, consistent with our analysis results." (PMID 33912448, 2021). "Survival curves showed that high expression of FOXM1,\ EXO1, KIF20A, TPX2, and CDC20 in melanoma patients with 5 of the top 10 hub genes was associated with reduced overall survival (OS)." (PMID 33912448, 2021). "FOXM1, EXO1, KIF20A, TPX2, and CDC20 are prognosis-associated core genes of melanoma, and their high expression correlates with the low prognosis of melanoma patients and can be used as biomarkers for melanoma diagnosis, treatment, and prognosis prediction." (PMID 33912448, 2021). "Therefore, we analyzed gene expression of the important HRR genes BRCA1, BRCA2, RAD51, and EXO1 after MAPKi treatment in MAPKi S, R, and RR A375 melanoma cells." (PMID 37674529, 2023). "FOXM1, KIF20A, TPX2, CDC20, and EXO1 could be used as biomarkers for melanoma diagnosis, treatment, and prognosis prediction." (PMID 33912448, 2021). "In conclusion, by combining the WGCNA analysis method with differentially expressed gene analysis, our study identified the genes FOXM1, KIF20A, TPX2, CDC20, and EXO1 highly correlated with survival melanoma patients and have the potential to serve as a prognostic biomarker in melanoma." (PMID 33912448, 2021).
Fanconi anemia (5 papers, 2013 to 2025). Fanconi anemia (FA) is a hereditary DNA repair disorder characterized by progressive pancytopenia with bone marrow failure, variable congenital malformations and predisposition to develop hematological or solid tumors. "Here, the authors find EXO1 loss as synthetic lethal with many DDR genes involved in various cancers, including genes from Fanconi Anaemia pathway, BRCA1-A complex, and spliceosome factor ZRSR2; such interactions represent potential clinical targets." (PMID 41006228, 2025). "Using CRISPR screening, we find EXO1 loss as synthetic lethal with many DDR genes somatically inactivated in cancers, including Fanconi Anaemia (FA) pathway and BRCA1-A complex genes." (PMID 41006228, 2025). "Importantly, we define notable cancer vulnerabilities amongst synthetic lethal hits with EXO1 loss, such as deficiencies in BRCA1-A complex factors, Fanconi Anaemia pathway genes and the splicing factor and tumour suppressor ZRSR2." (PMID 41006228, 2025).
gastric cancer (5 papers, 2013 to 2025). A primary or metastatic malignant neoplasm involving the stomach. "Interestingly, even in a panel comprising KRAS mutant and wild type gastric cancer cell lines, EXO1 showed higher expression in KRAS mutant cell lines (YCC16 and AGS) when compared to wild type cells (KATOIII)." (PMID 24147022, 2013). "We highlighted genes, including TPX2, MKI67, EXO1, and CTHRC1, as potential biomarkers for early diagnosis, prognostic evaluation, and therapeutic targeting in gastric cancer." (PMID 40445003, 2025). "We also found six genes in MSS tumors (EYS, FAT4, FSIP2, PCDHA1, RAD50, and RECQL4) and two in MSI tumors (EXO1 and FSIP2) that were clonally mutated in multiple patients and have not been previously identified as drivers of gastric cancer or other cancers." (PMID 36970058, 2022).
glioma (5 papers, 2018 to 2024). A benign or malignant brain and spinal cord tumor that arises from glial cells (astrocytes, oligodendrocytes, ependymal cells). "EXO1 is associated with shorter survival time and hyposensitivity to temozolomide treatment in glioma." (PMID 33634155, 2021). "After validation by RT-qPCR, IGF2BP3, NSUN7, EXO1, and FBXO17 had higher expression levels in glioma than controls." (PMID 33634155, 2021). "The results showed that ANG, EXO1, FBXO17, IGF2BP3, and NSUN7 displayed distinctly higher expression levels in glioma compared to controls (p < 0.05)." (PMID 33634155, 2021). "Our data confirmed the up-regulation of ANG, EXO1, FBXO17, IGF2BP3, and NSUN7 in glioma than normal samples (all p < 0.0001)." (PMID 33634155, 2021). "Our data suggested that IGF2BP3, NSUN7, EXO1, and FBXO17 were highly expressed in AC-, MES-, NPC-, and OPC-like malignant cells, which could be related to poor prognosis for glioma patients." (PMID 33634155, 2021).
invasive breast carcinoma (4 papers, 2013 to 2022). A carcinoma that infiltrates the breast parenchyma. "For breast invasive carcinoma (BRCA) patients with lower EXO1 expression, carboplatin treatment can promote patients' survival." (PMID 36255267, 2022). "Overexpression of DCAF13, DNMT3B, KPNA2, EXO1, FANCI, RACGAP1, and ZNF106 in invasive breast carcinoma patients showed poor survival, while overexpression of CDKN2A, SORBS1, and TP63 showed better survival." (PMID 32010179, 2019).
invasive ductal carcinoma (4 papers, 2013 to 2025). "We also found subtle elevation of EXO1 expression in invasive ductal breast carcinoma and metastatic breast tumors with modest statistical significance." (PMID 24147022, 2013). "Expression of EXO1 was higher in BRCA patients with pathologic stage II/III, infiltrating ductal carcinoma, age ≤60 years, PR-negative, ER-negative, HER2-positive, basal-like of PAM50 classification, and non-White race." (PMID 40433389, 2025). "Our findings were validated by another study to some extent, and they found DEPDC1, EXO1, RRM2 and some proteins had enhanced expression in the ductal carcinoma in situ and invasive ductal carcinoma." (PMID 31998560, 2020).
liver cancer (4 papers, 2011 to 2025). An epithelial or non-epithelial malignant neoplasm that arises from the liver.
breast tumors (3 papers, 2013 to 2022). "Univariate analysis revealed the significant association of EXO1 expression with relapse of breast tumors comparable to other individual clinical variables such as age, tumor size, grade, ER status, and lymph node status." (PMID 24147022, 2013). "Accordingly, EXO1 module genes’ expression is also observed to be higher in metastatic and basal breast tumors." (PMID 24147022, 2013). "Seven candidate genes including exonuclease 1 (EXO1) are consistently over expressed in breast tumors, specifically in high grade and aggressive breast tumors with poor clinical outcome." (PMID 24147022, 2013). "We derived a EXO1 co-expression module from the mRNA profiles of breast tumors which comprises 1q candidate genes and their co-expressed genes." (PMID 24147022, 2013). "All these support Ras/PI3K inhibition as a possible therapeutic strategy for EXO1 modular activated breast tumors." (PMID 24147022, 2013). "mRNA–drug connectivity analysis indicates inhibition of RAS/PI3K as a possible targeted therapeutic approach for the patients with activated EXO1 module in breast tumors." (PMID 24147022, 2013). "We also identified a possible therapeutic targeting approach for breast tumors with elevated EXO1 modular expression." (PMID 24147022, 2013). "In breast tumor mRNA profiles (GSE7390), the genes differentially expressed between elevated EXO1 expressing breast tumors (>60%) and reduced EXO1 expressing breast tumors (<10%) were short-listed." (PMID 24147022, 2013). "Further, consensus EXO1 co-expressing gene set was derived and is predicative of biological, clinical and pathological features of breast tumors." (PMID 24147022, 2013). "This shows that EXO1 modular genes are capable of predicting aggressive breast tumors irrespective of ER status." (PMID 24147022, 2013). "Elevated expression of EXO1 in ER negative and high grade breast tumors indicate the possible development of targeted therapeutics by targeting EXO1 module or its upstream regulators." (PMID 24147022, 2013). "EXO1 modular genes showed higher expression in ER negative and higher grade breast tumors." (PMID 24147022, 2013). "Thus, across multiple cohorts of breast tumors from various populations that were profiled across various microarray platforms, we observed highly consistent and elevated expression of EXO1 in high grade, basal, ER negative and PR negative subtypes." (PMID 24147022, 2013).
diabetes (3 papers, 2020 to 2025). "The present study revealed that SCD1 is involved in the regulation of hsa-miR-203a and hsa-miR-1908, which mediate the expression of FOS and EXO1 and may be associated with diabetic fracture." (PMID 32454462, 2020). "In summary, the newly proposed SCD1/miR-203a/FOS and SCD1/miR-1908/EXO1 pathways may enhance our understanding of the patho-mechanisms of osteogenesis in diabetes." (PMID 32454462, 2020). "The regulation of BM-MSCs of patients with type 2 diabetes mellitus (T2DM) by SCD-1 is a necessary condition for osteogenesis mediated through the miR-203a/FOS and miR-1908/EXO1 regulatory pathways." (PMID 33319811, 2020). "Furthermore, high expression levels of EXO1 were correlated with poor OS in patients with UCEC without radiation or hormonal therapy, or without diabetes." (PMID 40433389, 2025).
pancreatic cancer (3 papers, 2020 to 2025). "Furthermore, we tested the impact of EXO1 KO in the patient-derived FANCC-deficient pancreatic cancer cell line PL1140, which has a defect in FANCD2 monoubiquitylation that can be restored by complementation with wild-type FANCC." (PMID 41006228, 2025). "The p.H354R mutation in EXO1 has been shown to affect survival in pancreatic cancer." (PMID 32300177, 2020).
astrocytoma (2 papers, 2019 to 2024). "In addition, EXO1 is overexpressed in astrocytoma and is associated with an unfavourable prognosis." (PMID 39046429, 2024).
Bloom syndrome (2 papers, 2019 to 2020). Bloom syndrome (BSyn) is a rare chromosomal breakage syndrome characterized by a marked genetic instability associated with pre- and postnatal growth retardation, facial sun-sensitive telangiectatic erythema, increased susceptibility to infections, and predisposition to cancer. "After short, ssDNA is generated by CtIP/MRN complex, downstream nucleases such as exonuclease 1 (EXO1) or DNA replication helicase 2 and Bloom syndrome are further recruited to generate extended 3′-ssDNA for HR-mediated repair." (PMID 33097710, 2020). "The DSB site is bounded by several factors such as the MRN complex, EXO1 (exonuclease 1), DNA2-BLM (Bloom syndrome), BRCA1 and CTIP (CtBP-interacting protein) that contribute to DNA resection and formation of a 3′ single-strand DNA, which is then coated by proteins of replication A (RPA)." (PMID 31649878, 2019).
brain tumors (2 papers, 2023). "While most genes show elevated gene expression levels for all brain tumors, of interest is EXO1 and RPA3 which are only up-regulated in IDH-wt GBM samples." (PMID 36711972, 2023).
cerebral infarct (2 papers, 2012 to 2020). "At both 24 h and 3 d after cerebral infarct the expression of repair and recombination genes such as EXO1 was higher." (PMID 23284893, 2012). "Similarly, the TTC staining assay showed that the cerebral infarction of the EXO1 group exhibited a smaller infarct size of 9.915 ± 1.504% compared to 15.64 ± 2.354% in the pMCAO group (P < 0.05)." (PMID 33013286, 2020).
chondrosarcoma (2 papers, 2021 to 2023). A malignant cartilaginous matrix-producing mesenchymal neoplasm arising from the bone and soft tissue. "Supplementary to the HDR and NHEJ pathways, described in the literature for other cancer entities, the MMR pathway with the key players EXO1, MSH3, and PCNA, is also clearly activated in chondrosarcoma cells after proton application." (PMID 34916568, 2021). "In a previous work, we were able to show that, in addition to homologous-directed repair (HDR) and non-homologous end joining (NHEJ), the mismatch-mediated repair (MMR) pathway with the main players EXO1, MSH3, and PCNA were clearly activated in chondrosarcoma cells after proton application." (PMID 36768638, 2023).
glioblastoma (2 papers, 2020 to 2025). The most malignant astrocytic tumor (WHO grade IV). "Intriguingly, EXO1 deficiency does not lead to TMZ resistance in TK6 cells and instead somewhat hyper-sensitizes to TMZ, which is in disagreement with the result of CRISPR-based genome-wide screen carried out in TMZ-treated MGMT-negative glioblastomas." (PMID 39656916, 2025).
hereditary nonpolyposis colorectal cancer (2 papers, 2022). "In humans, germline mutations in EXO1 have been associated with hereditary nonpolyposis colorectal cancer/Lynch syndrome (HNPCC/LS)." (PMID 35849338, 2022).